HTRA3 (HtrA serine peptidase 3)
Description:
Serine protease that cleaves beta-casein/CSN2 as well as several extracellular matrix (ECM) proteoglycans such as decorin/DCN, biglycan/BGN and fibronectin/FN1. Inhibits signaling mediated by TGF-beta family proteins possibly indirectly by degradation of these ECM proteoglycans (By similarity). May act as a tumor suppressor. Negatively regulates, in vitro, trophoblast invasion during placental development and may be involved in the development of the placenta in vivo. May also have a role in ovarian development, granulosa cell differentiation and luteinization.
Synonyms: PRSP; Tasp
Tractability: Antibody: UniProt places it where antibodies can reach, with high confidence; UniProt predicts a signal peptide or a membrane-spanning region; its Gene Ontology location is reachable by antibodies, with medium confidence.
Gene: Protein-coding gene on chromosome 4 (8,269,749 to 8,307,110, forward strand). Ensembl gene ENSG00000170801.
Subcellular location: Secreted
Subcellular location (Human Protein Atlas): Vesicles; Predicted to be secreted
Gene Ontology:
Molecular function: endopeptidase activity; identical protein binding; protein binding; serine-type peptidase activity; serine-type endopeptidase activity
Biological process: proteolysis; negative regulation of BMP signaling pathway; negative regulation of transforming growth factor beta receptor signaling pathway
Cellular component: extracellular region
Genetic constraint (gnomAD): Loss-of-function variants: 36 observed, 34.32 expected, observed/expected ratio (o/e) 1.05, 90% interval 0.8 to 1.38. The upper end of that interval is the gene's LOEUF score, 1.38, which puts it in group 5 of 6, group 1 being the genes least tolerant of losing a copy. Missense variants: 621 observed, 587.72 expected, observed/expected ratio (o/e) 1.06, 90% interval 0.99 to 1.13. Synonymous variants: 291 observed, 260.02 expected, observed/expected ratio (o/e) 1.12, 90% interval 1.02 to 1.23.
Homologues: Orthologues: macaque HTRA3 (99% identical), pig HTRA3 (93% identical), mouse Htra3 (93% identical), rat Htra3 (92% identical), guinea pig HTRA3 (78% identical), tropical clawed frog htra3 (77% identical), chimpanzee HTRA3 (76% identical), dog HTRA3 (72% identical), zebrafish htra3a (68% identical), zebrafish HTRA3 (67% identical). Paralogues in human: HTRA1 (60% identical), HTRA4 (50% identical), HTRA2 (41% identical).
Diseases named in the same sentence as HTRA3 in open-access papers:
HTRA3 is named in the same sentence as 43 diseases in open-access papers, as found by Europe PMC text mining. Sharing a sentence is not in itself a finding about the gene and the disease. The quoted sentences say what the papers report.
lung carcinoma (10 papers, 2012 to 2025). "HTRA3 was first shown to be associated with cancer in a report demonstrating that it may act as a tumor suppressor, which is a pro-apoptotic protease that promotes drug-induced cytotoxic effects in lung cancer cells." (PMID 33425760, 2020). "Various studies have highlighted a link between HTRA3 and lung cancer, with HTRA3 being downregulated in lung tumour tissue, and higher HTRA3 levels correlating with lower recurrence and longer disease-free survival in lung cancer patients." (PMID 40716152, 2025). "Using our signature, we identified HTRA3 as a potential novel effector of BACH1's pro-migratory effect in human lung cancer cells." (PMID 40716152, 2025). "The signature works in most cells (but not in all), demonstrating that induction of HMOX1, ZNF469 and HTRA3 is a strong surrogate for BACH1 depletion in lung cancer cells and a good pan-tissue BACH1 signature." (PMID 40716152, 2025). "HTRA3 is also down-regulated in endometrial, ovarian, and lung cancers and upregulated in thyroid tumors, suggesting that HTRA3 is involved in the pathogenesis of cancers." (PMID 37185732, 2023). "HtrA3 can also inhibit lung cancer cell invasion, and the levels of HtrA3 negatively correlate to the increased risk of postoperative recurrence of non-small-cell lung cancer." (PMID 34639128, 2021). "In lung cancer, HtrA3 is shown to promote cell death following treatment with chemotherapeutic drugs, and HTRA3 knockdown renders these cells resistant to anti-tumour drugs." (PMID 34639128, 2021). "HTRA3 is reported to be downregulated in many cancer cell lines and primary tumours, including ovarian, endometrial, breast and lung cancers." (PMID 34639128, 2021). "Downregulation of HTRA3 was noted in ovarian tumors, endometrial and lung cancers, and antagonism of HTRA3 and TGFβ1 (Tumor growth factor Beta) contributes to metastasis of non-small cell lung cancer." (PMID 32560402, 2020). "High-Temperature Requirement Factor A3 (HtrA3) expression is reduced in lung cancer cell lines and lung tumors." (PMID 28587272, 2017). "In one lung cancer study, HTRA3 expression promoted mitochondrial cell death and chemotherapy-induced cytotoxicity." (PMID 27166271, 2016). "HTRA3 was significantly down-regulated in lung cancer tissues compared with normal lung tissues, and only six tumor cases(7.7%) exhibited relatively high levels of HTRA3 (P < 0.001)." (PMID 27166271, 2016). "In particular, the present study strongly indicates that HTRA3 negatively regulates lung cancer cell invasiveness." (PMID 27166271, 2016). "HtrA3 is downregulated in lung cancers through smoking-induced DNA methylation and this downregulation increases cancer cell longevity." (PMID 23049902, 2012). "HtrA3 downregulation in lung cancer also contributes to resistance to chemotherapeutic treatments such as etoposide and cisplatin." (PMID 23049902, 2012). "Furthermore, HTRA3 restricts lung cancer cell migration and invasion further supporting the new link we established between the reduced migration observed in BACH1-depleted cells and HTRA3 upregulation." (PMID 40716152, 2025). "The expression of HTRA3 in lung cancer tissue was significantly down-regulated." (PMID 33425760, 2020). "HTRA3 promotes drug-induced apoptosis through XIAP cleavage in lung cancer cells." (PMID 33425760, 2020). "In summary, HTRA3 is downregulated in lung cancer and could be both an attractive predictor of postoperative recurrence and a treatment target for a subset of patients with NSCLC." (PMID 27166271, 2016). "In addition, the expression of HTRA3 was reduced in smoking-related lung cancers, and this was shown to result from methylation within its first exon." (PMID 27166271, 2016). "From the validated three gene signature we focused on the two newly identified BACH1 target genes, HTRA3 and ZNF469, both of which are highly induced by BACH1 depletion in lung cancer cells." (PMID 40716152, 2025).
lung carcinoma (continued). "Furthermore, HtrA3 is an inhibitor of the bone morphogenetic protein pathway, linked to EMT, and has been implicated as a tumour suppressor gene during cancer progression in many cancers, such as lung cancer, ovarian cancer, breast cancer and colorectal cancer." (PMID 32971738, 2020). "In our semi-quantitative analysis, the expression score for HTRA3 protein was significantly lower in lung cancer specimens than in non-NSCLC specimens (P < 0.001)." (PMID 27166271, 2016). "To validate our clinical findings and clarify the specific function of HTRA3 in NSCLC, we investigated whether HTRA3 would suppress or enhance lung cancer cell invasion." (PMID 27166271, 2016). "Although the function of HTRA3 in lung cancer has not been fully identified, a previous study suggested that HTRA3 is a mitochondrial protease that promotes etoposide- and cisplatin-induced cytotoxicity by activating the apoptotic pathway." (PMID 27166271, 2016). "However, our data show that in our system HTRA3 induction is necessary but not sufficient for the anti-migratory effect observed in lung cancer cells upon BACH1-depletion, suggesting that BACH1 likely regulates migration through a multifactorial mechanism involving additional targets." (PMID 40716152, 2025).
endometrial cancer (6 papers, 2012 to 2021). Primary or metastatic malignant neoplasm involving the endometrium (mucous membrane that lines the endometrial cavity). "A recent study on Endometrial cancer demonstrated hypoxia reduced the content of HtrA3, and silencing HtrA3 promoted Endometrial cancer cell migration, and as the degree of hypoxia increases in Endometrial cancer." (PMID 33462352, 2021). "Previous studies have elucidated the low expression of HTRA3 in endometrial carcinoma and ovarian cancer had anti-tumor effect." (PMID 33425760, 2020). "In a previous study, HTRA3 expression was found to decrease with increasing stages of endometrial cancer." (PMID 27166271, 2016). "Narkiewicz and colleagues studied HtrA1, HtrA2 and HtrA3 mRNA and protein by two semi-quantitative techniques, RT-PCR (mRNA) and WB (protein), in 124 women; 88 with endometrial cancer and 36 with normal endometrium." (PMID 26035313, 2015). "A study has reported that HTRA3 expression was reduced in endometrial hyperplasia as well as endometrial cancer, which suggests the overexpression of HTRA3 may play a protective role in EC." (PMID 32608475, 2020). "In endometrial cancer, a negative correlation between HTRA3 and TGF-β1 protein levels was identified." (PMID 27166271, 2016).
preeclampsia (6 papers, 2012 to 2022). Preeclampsia is a hypertensive disorder of pregnancy that is characterized by new-onset hypertension with proteinuria presenting after 20 weeks of gestation, and depending on mild or severe forms may initially present with severe headache, visual disturbances, and hyperreflexia. "HtrA3 is a protease involved in the promotion of apoptosis and embryo implantation and linked to human diseases such as cancer and preeclampsia." (PMID 26110759, 2015). "Recently, HtrA3 was identified as a potential diagnostic marker for early detection of preeclampsia, a life-threatening pregnancy-specific disorder." (PMID 23049902, 2012). "In contrast, sustained expression of HtrA3 in the first trimester of pregnancy is associated with the development of preeclampsia." (PMID 23049902, 2012). "Dysregulation of HtrA3 is associated with the development of a number of diseases including cancer and preeclampsia." (PMID 23049902, 2012). "These HtrA3 mAbs provide critical tools for the diagnosis of preeclampsia and possibly other human diseases associated with HtrA3 dysregulation, and will enable further characterisation of HtrA3 isoform-specific biology." (PMID 23049902, 2012). "HtrA3 negatively regulates trophoblast invasion during placental development and abnormal levels of HtrA3 during early pregnancy in women are associated with risks of developing preeclampsia (a severe pregnancy-specific disorder)." (PMID 25248123, 2014). "Preeclampsia is related, and the severity of preeclampsia can be inferred based on the content of HtrA3." (PMID 35035835, 2022). "It was found that the levels of HtrA3 in the maternal serum and placental tissues of severe preeclampsia and preeclampsia were higher than those in the control group." (PMID 35035835, 2022). "Studies have found that HtrA3 is most produced in the first 3 months of pregnancy, and the abnormal increase in serum HtrA3 at 13-14 weeks of gestation is related to preeclampsia." (PMID 35035835, 2022). "The 15-week reduction in HtrA3 levels can be used to early predict the birth of late-onset preeclampsia and small-for-gestational-age infants and provide a basis for intervention and early treatment." (PMID 35035835, 2022). "The control found that pregnant women with late-onset preeclampsia or small-for-gestational-age infants had a significant reduction in serum HtrA3 levels at 15 weeks of gestation." (PMID 35035835, 2022). "There is a negative correlation between the level of HtrA3 and TGF-β2 and the birthweight of newborns both in maternal plasma and placenta tissue in preeclampsia and positive correlation between HtrA3 and TGF-β2 levels and S/D." (PMID 35035835, 2022). "At present, the research on HtrA3 and preeclampsia mainly focuses on the early and second trimesters." (PMID 35035835, 2022). "Women who are destined to develop preeclampsia have significantly higher levels of serum HtrA3 at 13–14 weeks of gestation, well before clinical symptoms manifest." (PMID 34639128, 2021). "Modulating HtrA3 activity using 6G6 or 10H10 in pathological conditions such as preeclampsia, arthritis and tumor progression would provide novel therapeutic applications." (PMID 25248123, 2014). "Placental HtrA3 is secreted into the maternal circulation and its serum levels are higher during early pregnancy in women who later develop preeclampsia." (PMID 25248123, 2014). "The HtrA3 AlphaLISA detected significantly higher serum levels of HtrA3 in women at 13–14 weeks of gestation who subsequently developed preeclampsia compared to gestational-age matched controls." (PMID 23049902, 2012). "Using western blotting, serum HtrA3 levels at this gestation were found to be significantly higher in women who subsequently developed preeclampsia (Preeclampsia, n = 8) than those who had normal pregnancies (Normal, n = 8)." (PMID 23049902, 2012).
preeclampsia (continued). "The 10H10C/2C4B AlphaLISA recognising all HtrA3 isoforms detects significantly higher levels of HtrA3 in serum at early gestation in pregnant women who subsequently developed preeclampsia than controls as previously published." (PMID 23049902, 2012). "A neutralising mAb would have implications for therapeutic opportunities in diseases where HtrA3 is abnormally higher than normal such as preeclampsia." (PMID 23049902, 2012). "Future studies will utilise HtrA3 AlphaLISAs to screen a large number of appropriate serum samples to establish the robustness of HtrA3 as an early marker for preeclampsia." (PMID 23049902, 2012). "After being validated on recombinant HtrA3 proteins, the optimised assays were applied to first trimester serum samples collected from women who subsequently developed preeclampsia later in pregnancy." (PMID 23049902, 2012). "The number of HtrA3-positive staining in the placenta of patients with severe preeclampsia is more than that of preeclampsia, and the staining is deeper, and both of them are more than the number of positive cells in the placenta of normal pregnant women, and the staining is deeper." (PMID 35035835, 2022). "Dysregulation of HtrA3 has been observed in a number of diseases including cancer and preeclampsia." (PMID 26110759, 2015). "Notably, the assay for both HtrA3 isoforms detected significantly higher levels of HtrA3 at 13–14 weeks of gestation in pregnant women who subsequently developed preeclampsia later in gestation, compared with women who had a normal pregnancy." (PMID 23049902, 2012). "It is possible that combining HtrA3 detection with other markers may strengthen the power of preeclampsia detection." (PMID 23049902, 2012). "As persistently high serum levels of HtrA3 are detected at the end of the first trimester in pregnant women who subsequently develop preeclampsia, we have proposed that monitoring HtrA3 in maternal blood during early pregnancy would identify women at risk for preeclampsia." (PMID 23049902, 2012). "In summary, the abnormally high expression of HtrA3 and TGF-β2 is correlated with preeclampsia and related clinical indicators." (PMID 35035835, 2022). "When trophoblast cells are planted and enter the myometrium to promote the formation of the placenta, HtrA3 can inhibit this process by regulating TGF-β signaling and has a certain relationship with the pathogenesis of preeclampsia." (PMID 35035835, 2022). "The correlation was found between the levels of HtrA3 and TGF-β 2 and preeclampsia (PE)." (PMID 35035835, 2022). "The purpose of this study was to detect HtrA3 and TGF-β2 in different parts of the third trimester (maternal serum, placenta) in order to further explore the correlation between the expression levels of HtrA3 and TGF-β2 in the third trimester of pregnancy and preeclampsia and on neonatal outcomes." (PMID 35035835, 2022). "HtrA3 and TGF-β2 are related to the increase of the S/D value, which is helpful for the early diagnosis of preeclampsia and small-for-gestational-age infants, and can affect the birthweight of newborns and may even affect the distribution and content of body fat in the future." (PMID 35035835, 2022). "Whether the expression of HtrA3 in various detection methods in the third trimester is related to preeclampsia and neonatal outcomes has not been reported yet." (PMID 35035835, 2022).
non-small cell lung carcinoma (5 papers, 2016 to 2022). A group of at least three distinct histological types of lung cancer, including non-small cell squamous cell carcinoma, adenocarcinoma, and large cell carcinoma. "For example, in non-small cell lung cancer, over-expression of HTRA3 inhibited TGF-β1 to suppress tumor metastasis." (PMID 35445008, 2022). "In non-small cell lung cancer cell lines, exogenous transforming growth factor β-1 significantly reduced HTRA3 expression during EMT." (PMID 33425760, 2020). "Overexpressed HTRA3 inhibits the carcinogenic role of TGFβ1 and thus inhibits metastasis in the early stages of non-small cell lung cancer." (PMID 33425760, 2020). "In non-small cell lung cancer (NSCLS) cell lines, overexpression of HTRA3 inhibits the carcinogenesis of TGF-β1, thus inhibiting tumor metastasis in the early stage of cancer." (PMID 33425760, 2020).
ovarian carcinoma (5 papers, 2012 to 2021). A malignant neoplasm originating from the surface ovarian epithelium. "The expression of HTRA3 is also dramatically reduced in endometrial and ovarian cancers." (PMID 27166271, 2016). "More recently, HTRA3 levels were found to correlate with the malignant subtypes of ovarian cancers." (PMID 27166271, 2016). "Correspondingly, HtrA3 protein is also significantly lower in ovarian cancer tissues, consistent with the theory that HtrA3 may play an important role in promoting programmed cell death in ovarian cancer." (PMID 34639128, 2021).
breast carcinoma (4 papers, 2016 to 2025). "In contrast, DEGs associated with inhibiting breast cancer metastasis (HTRA3 and NOTCH3) were negatively correlated with 23 metabolites and positively correlated with 39 metabolites." (PMID 41179294, 2025). "In breast cancer, the expression of HTRA3 was significantly lower in stage III than in stages I and II." (PMID 27166271, 2016). "Interestingly, MDH2 overexpression upregulated several genes associated with breast cancer metastasis (IL13RA2, MMP3, PTGS1, SYK, VCAN, and FLT1) and downregulated several genes associated with metastasis suppression (NOTCH3 and HTRA3)." (PMID 41179294, 2025). "Specifically, we observed up-regulation of genes that drive breast cancer metastasis (IL13RA2, MMP3, PTGS1, SYK, VCAN, and FLT1) and downregulation of metastasis-associated suppressor genes (NOTCH3, and HTRA3)." (PMID 41179294, 2025). "Indeed, in breast cancer, the expression of HTRA3 negatively correlated with lymph node metastasis." (PMID 27166271, 2016). "The expression of HTRA3 was negatively correlated with lymph node metastasis in breast cancer, but not with positive or negative expression of ER and PR." (PMID 33425760, 2020). "HTRA3 expression was negatively correlated with lymph node metastasis in breast cancer, but not with positive or negative expression of ER and PR." (PMID 33425760, 2020).
pancreatic cancer (4 papers, 2020 to 2025). "The ectopic expression of HTRA3 leaded to the decrease of cell proliferation and the increase of the expression of apoptotic protein Bax, suggesting that HTRA3 has anti-tumor effect on pancreatic cancer cells." (PMID 33425760, 2020). "Moreover, pancreatic cancer growth is inhibited by paeoniflorin, which does so through increasing HTRA3." (PMID 36339551, 2022). "The ectopic expression of HTRA3 in pancreatic cancer leads to the decrease of cell proliferation and the increase of the expression of apoptotic protein Bax, suggesting that HTRA3 has anti-tumor effect on pancreatic cancer cells." (PMID 33425760, 2020).